INS (insulin)
Diseases named in the same sentence as INS in open-access papers (continued):
Sharing a sentence is not in itself a finding about the gene and the disease.
type 2 diabetes (continued). "Type 2 diabetes is characterized mainly by defects in insulin action, β-cell dysfunction and chronic inflammation." (PMID 33320449, 2021). "A randomized crossover study showed that interrupting the sitting duration with standing and light-intensity walking effectively improved daily glucose levels and insulin sensitivity in type 2 diabetes." (PMID 34578968, 2021). "In a dietary‐induced obese mouse model of type 2 diabetes, a single treatment with mCPP rapidly improved glucose and insulin tolerance over the next 2 hours." (PMID 33909316, 2021). "In patients with Type 2 diabetes (T2D), insulin is either produced in insufficient quantities so the response to insulin is weak or it is produced in normal amounts, but the target organs become insulin resistant." (PMID 33580013, 2021). "Gestational diabetes mellitus (GDM) is a complication of pregnancy that has similar characteristics as type 2 diabetes mellitus (T2D), such as glucose intolerance, insulin resistance, and impaired insulin secretion." (PMID 34557221, 2021). "put forward the theory of “brain starvation” in patients with type 2 diabetes, due to concurrent hyperinsulinemia and relative hypoglycemia due to insulin resistance resulting in apoptosis of healthy neurons from catabolic degeneration." (PMID 33763024, 2021). "Metformin canonically facilitates improved insulin sensitivity and overall glucose uptake for type 2 diabetes (T2D) patients, but recent studies show the potential of repositioning metformin due to its anti-cancer properties." (PMID 34829914, 2021). "An ethanol extract of HRS significantly inhibited DPP-4 activity, increased insulin release, and thus, improved glucose tolerance in type 2 diabetic rats." (PMID 34203048, 2021). "Simplified treatment regimens have shown improvements in patient-reported outcomes in type 2 diabetes, but direct studies in T1D are difficult due to the necessity of insulin therapy." (PMID 37745178, 2021). "Metformin is a drug commonly prescribed to treat patients with type 2 diabetes and obesity, the benefic effects of which enhance insulin sensitivity, induce glycolysis, and suppress gluconeogenesis in the liver." (PMID 34572007, 2021). "Reduction of NLRP3 expression in adipose tissue was correlated with improvement of insulin sensitivity in type 2 diabetes patients." (PMID 34832960, 2021). "Evidence from a systematic review of 253 articles indicated that ingestion of caffeine (approximately 200–500 mg) significantly increases blood glucose concentration by 16–28% and decreases insulin sensitivity by 14–37% among individuals with type II diabetes." (PMID 34200398, 2021). "Profiles of fasting insulin, free fatty acid, and brain weight in high-fat diet and streptozotocin-induced type 2 diabetic rats treated with alpha-lipoic acid for 13 weeks." (PMID 34867302, 2021). "Previous research reported that the probable effects of a low-GI diet are lowering insulin secretion in type 2 diabetes and decreasing daily insulin requirements in type 1 diabetes." (PMID 33803775, 2021). "Thiazolidinediones (TZDs) are synthetic PPARγ ligands with robust insulin-sensitizing activities, and they are used in the treatment of type 2 diabetes." (PMID 34445679, 2021). "The objective of this study was to compare the use of pens vs. syringes to apply insulin among elderly with uncontrolled type 2 diabetes treated in the public health system of southern Brazil." (PMID 34118981, 2021). "The risk of dementia is also higher in patients with type 2 diabetes mellitus (T2DM), possibly due to vascular changes, alterations in glucose metabolism, and insulin signaling possibly resulting in neurodegeneration." (PMID 34280191, 2021). "Overweight CF patients are more likely to be insulin resistant, taking on features of type 2 diabetes." (PMID 34868883, 2021).
type 2 diabetes (continued). "Activation of NMDAR leads to failure of functions of the β-cell in the pancreas by reducing the mass of the β-cell, insulin secretion leads to type-2 diabetes due to the higher intake of glutamate." (PMID 34026558, 2021). "Dysfunctional glucose-mediated insulin release is a characteristic of type 2 diabetes, and induces hyperglycemia." (PMID 34202399, 2021). "Approximately 25% of patients with type 2 diabetes (T2D) taking insulin for >5 years have severe hypoglycemic episodes, which is the same as the rate of severe hypoglycemic episodes in adults with type 1 diabetes diagnosed within 5 years." (PMID 34744863, 2021). "Some investigations showed a beneficial effect of insulin treatment on diabetic atherosclerosis and macrovascular complications in type 2 diabetes." (PMID 33598483, 2021). "The insulin-sensitizer pioglitazone exerts its cardiometabolic benefits in type 2 diabetes (T2D) through a redistribution of body fat, from ectopic and visceral areas to subcutaneous adipose depots." (PMID 34925073, 2021). "Obesity is characterized by a chronic low-grade inflammation that is initiated in adipose tissue (AT) and interferes with insulin signaling and ultimately contributes to type 2 diabetes (T2D)." (PMID 34684461, 2021). "In humans and rodent models, IL-1β is tied to the pancreatic β cell dysfunction of type II diabetes through the effect of IL-1β to inhibit glucose-stimulated insulin secretion." (PMID 34944138, 2021). "KEGG analysis further showed a significant enrichment in type 2 diabetes, insulin secretion and glycerolipid metabolism pathways." (PMID 34776961, 2021). "Ideally, such a treatment for type 2 diabetes, with the reprogramming of α cells into insulin-producing cells, would be accompanied by lifestyle modification." (PMID 34882233, 2021). "Cold acclimation has been shown to have beneficial metabolic effects, including improved insulin sensitivity in patients with type 2 diabetes." (PMID 33750795, 2021). "The beneficial effects of regular aerobic and resistance exercises for patients with type 2 diabetes, which include improved glycemic control and reduced insulin resistance, have been well established by many epidemiological studies and meta‐analyses." (PMID 33955191, 2021). "This soluble combination of two individual insulin analogs can be administered once or twice daily to people with type 2 diabetes and has demonstrated its safety and efficacy in clinical studies." (PMID 34564455, 2021). "The results showed that BBR treatment can significantly increase the serum insulin level, effectively improve the phenomenon of atrophied islet area and decrease insulin synthesis in type 2 diabetic model mice." (PMID 34630099, 2021). "METTL3 was up-regulated in patients with type 2 diabetes and mice with high-fat diet, and inhibited insulin sensitivity and promoted fatty acid metabolism." (PMID 34503454, 2021). "On the other hand, obesity, a major risk factor for type 2 diabetes mellitus (T2DM), could lead to the dysfunction of β cell in the pancreas, which is characterized by abnormalities in insulin synthesis and secretion." (PMID 34803706, 2021). "The prevalence of type 2 diabetes has increased alarmingly in recent years, therefore the development of new effective treatment options to increase insulin sensitivity is a challenge for many researchers." (PMID 34067862, 2021). "The higher prevalence of type 2 diabetes in Asians is related to less insulin secretion and β–cell mass than Caucasians." (PMID 34359426, 2021). "In support of this new model, insulin secretion has been found to be elevated before the development of hyperglycemia in a longitudinal study of Rhesus monkeys, developing a form of type 2 diabetes, which appears to be very similar to that found in humans." (PMID 34360563, 2021). "Type 2 diabetes is a syndrome defined by hyperglycaemia that is the result of various degrees of pancreatic β-cell failure and reduced insulin sensitivity." (PMID 33387681, 2021).
type 2 diabetes (continued). "Type 2 diabetes (T2D) is characterized by the body’s resistance or insufficient production of insulin." (PMID 34783668, 2021). "Model of long-term type 2 diabetes was used to detect the availability of PCK2 in the situation when a substantially lower amount of insulin is synthesized by this type of cells." (PMID 34203686, 2021). "Calcium level was revealed by FUGUE and Z-Score (>13 odds ratio), in line with essential role of calcium levels in regulation and release of insulin by the pancreas and in its implication during the development of type II diabetes." (PMID 34270548, 2021). "Type 2 diabetes is a prevalent chronic metabolic disorder that represents a global growing healthcare burden, characterized mainly by resistance to insulin action along with insufficient secretion." (PMID 34360895, 2021). "In type 2 diabetes, the ability of insulin to suppress endogenous glucose production is impaired, and increased fasting and postprandial glucagon levels stimulate endogenous glucose production even further." (PMID 34382579, 2021). "In people with type 2 diabetes, tissues are insensitive to insulin, resulting in the rise of blood glucose due to increased liver production and a lack of uptake." (PMID 34631141, 2021). "According to research, the HOMA-IR index divided by the product of insulin and glucose concentrations by a factor is a widely accepted score for analyzing type 2 diabetes." (PMID 34836432, 2021). "Taking into account carbohydrate metabolism, an improvement in glucose tolerance and/or insulin sensitivity was observed in overweight people and patients with type 2 diabetes." (PMID 33801152, 2021). "The efficacy of exercise was demonstrated also for dynamic measures of insulin sensitivity (i.e., clamp, oral glucose tolerance test, and insulin tolerance test), in patients with type 2 diabetes." (PMID 33960110, 2021). "In fact, type 2 diabetics have lower hepatic ATP concentrations, and both peripheral and hepatic insulin sensitivity are significantly correlated with liver ATP concentrations." (PMID 34192533, 2021). "Androgens have a complex role in the regulation of insulin sensitivity in the pathogenesis of type 2 diabetes." (PMID 34987473, 2021). "A recent study 31 found that 21% of insulin‐initiating individuals after the age of 30 with register‐classified type 2 diabetes based on their debut age and instead had type 1 diabetes." (PMID 34277957, 2021). "In type 2 diabetes, the majority of the patients used a combination of insulin and oral glucose-lowering medication (59.2%)." (PMID 34134677, 2021). "In type 2 diabetes, endothelial dysfunction is characterized by reduced insulin signaling and increased transendothelial transport of fatty acids (FA)." (PMID 34214082, 2021). "The mTOR signaling pathway seems to be involved in both type 1 and type 2 diabetes, insulin production being reduced in type 1 diabetes due to the destruction of pancreatic β cells while insulin resistance occurs in type 2." (PMID 34069618, 2021). "In type 2 diabetes, a clear relationship between residual insulin and DR was initially more difficult to show." (PMID 34912295, 2021). "Assessment of several ethnic groups has shown a progressive reduction in β-cell function from normal to impaired glucose tolerance and subsequently to type-2 diabetes, accompanied by a decline in insulin sensitivity." (PMID 34017668, 2021). "We reported that the squid trypsin inhibitor did not inhibit elevated blood glucose in healthy Wistar rats, but only in GK rats that were a model of type 2 diabetes, and its effect was related to an improvement in insulin secretion in GK rats." (PMID 34677483, 2021). "Generally AGE lowering interventions have improved insulin sensitivity in humans who are obese or with type 2 diabetes." (PMID 34203471, 2021). "Type 2 diabetes mellitus (T2DM) is a severe disease characterized by elevated glucose levels due to insulin resistance or inadequate insulin secretion." (PMID 33280239, 2021).
type 2 diabetes (continued). "Type 2 diabetes mellitus (T2DM) is a genetically heterogeneous metabolic disorder characterized by chronic hyperglycemia due to impaired insulin secretion and sensitivity influenced by genetic and environmental factors." (PMID 34853793, 2021). "Type-2 diabetes is a progressive condition in which the body grows resistant to the usual impact of insulin and/or gradually loses the ability of the pancreas to produce enough insulin." (PMID 35540699, 2021). "Fully closed-loop improved glucose control and reduced hypoglycemia compared with standard insulin therapy in adult outpatients with type 2 diabetes requiring dialysis." (PMID 34349267, 2021). "Disruptions in the normal function of adipose tissue lead to defective glucose homeostasis in liver and skeletal muscles, which in turn result in systemic insulin resistance and ultimately the onset of type 2 diabetes." (PMID 33917607, 2021). "The aim of our study was to investigate the effect of imatinib on two endothelial functions involved in type 2 diabetes: insulin-stimulated vasodilation of resistance arteries and endothelial fatty acid uptake." (PMID 34214082, 2021). "Smoking initiation, smoking cessation, lifetime smoking, age at smoking initiation, alcoholic drinks per week, body mass index, systolic and diastolic blood pressure, type 2 diabetes, glycated hemoglobin, fasting glucose, and fasting insulin." (PMID 34734970, 2021). "There will also be an increase in the number of strains of the genus Lactobacillus, leading to intolerance to insulin action and a clinical sign of type 2 diabetes." (PMID 34201465, 2021). "Mice with targeted mutation in the 5-HTR2C gene resulted in insulin resistance and type 2 diabetes (T2D), with antecedent hyperphagia and obesity, suggesting an interaction of insulin with 5-HTR2C on energy metabolism." (PMID 34367066, 2021). "Type 2 diabetes (T2D) is a chronic metabolic disorder characterized by reduced insulin sensitivity throughout the body contributing to hyperglycemia." (PMID 35229063, 2021). "Search terms included “intestinal barrier function”, “type 2 diabetes”, “intestinal immune system”, “obesity”, “lipopolysaccharides”, “leaky gut”, “intestinal epithelial cells”, “glucose intolerance”, “insulin resistance” and were used." (PMID 35145486, 2021). "The levels of lipid profile, glucose, insulin, and liver enzymes were measured as metabolic factors to evaluate type 2 diabetes status." (PMID 34804425, 2021). "These actions contribute to improving insulin sensitivity and glucose homeostasis in a patient with type 2 diabetes." (PMID 33467194, 2021). "i.e. in individuals with type 2 diabetes and endurance-trained athletes, and that these proteins positively correlate to aerobic capacity and insulin sensitivity." (PMID 33258025, 2021). "Studies investigating the hepatic ER proteome in animal models of type 2 diabetes (db/db mice) show severe disruption of the normal functions of the ER in the liver of diabetic mice with great impact on hepatic insulin sensitivity." (PMID 34679670, 2021). "Emerging evidence supports the roles of UPR and ER stress in the pathogenesis of pancreatic beta-cell dysfunction, insulin resistance, and apoptosis in type II diabetes." (PMID 34299638, 2021). "Skeletal muscle is the major site of glucose uptake in the postprandial state, and insulin resistance in skeletal muscles is shown to be the primary defect in type 2 diabetes." (PMID 34943946, 2021). "The pathophysiology of type 2 diabetes involves defects in multiple components of insulin homeostasis." (PMID 34206745, 2021). "Data from many studies suggest not only correlative, but also causative association between higher activity of proinflammatory processes in adipose tissue and impair insulin metabolism, insulin resistance, and diabetes type 2." (PMID 33917519, 2021).
type 2 diabetes (continued). "On the other hand, insulin treatment has a specific position in the treatment of type 2 diabetes in Sweden, where its use is prioritized in the guidelines and common even in patients with dementia." (PMID 34857046, 2021). "Patients with type 1 and type 2 diabetes who receive Detemir insulin have less weight gain than those using NPH and glargine insulin." (PMID 34904015, 2021). "It was reported that RS3 showed the therapeutic effect on Type 2 diabetes through improving dyslipidemia, reducing insulin resistance, and increasing insulin sensitivity." (PMID 34200160, 2021). "ECs from patients with type 2 diabetes are resistant to both insulin- and IGF-1–mediated eNOS phosphorylation." (PMID 34420367, 2021). "Most research to date indicates that people with type 2 diabetes who engage in both aerobic and resistance exercise see the greatest improvements in insulin sensitivity." (PMID 34721838, 2021). "In obesity, skeletal muscle, the main tissue responsible for insulin‐mediated glucose uptake, exhibits dysregulation of insulin signaling, glucose uptake, lipid metabolism, and mitochondrial function, thus, promoting type 2 diabetes." (PMID 33433056, 2021). "Sodium-glucose cotransporter-2 (SGLT2) inhibitors, which act independently of insulin, represent newly developed oral antidiabetic drugs that are practiced for type 2 diabetes mellitus (T2DM) management." (PMID 34790128, 2021). "Once-weekly insulin treatment with insulin icodec was demonstrated to be effective at lowering HbA1c levels in adults with type 2 diabetes." (PMID 37745178, 2021). "Randomized trials showed that among high-risk or older patients with type 1 or type 2 diabetes, CGM-guided insulin therapy was more effective than usual care in improving glycemic control." (PMID 34575228, 2021). "PUE has been utilized for the treatment of diabetes mellitus in China since the 1990s to enhance the glucose uptake into the insulin cell, and subsequently downregulate the blood glucose levels in the type II diabetes treatment." (PMID 33477727, 2021). "Type 2 diabetes is a form of the disease characterized by three different conditions in the human body: high levels of glucose in blood, a decrease in the amount of insulin, and an insulin resistance." (PMID 33668203, 2021). "By inhibiting the hypothalamic NPY signaling pathway, insulin secretion will be increased, thus participating in the pathogenesis of type 2 diabetes." (PMID 34307371, 2021). "They contain polyunsaturated fatty acids (PUFA) so they can be recommended as a natural remedy to treat type 2 diabetes as they increase the insulin levels that ultimately reduce the blood glucose levels." (PMID 34540481, 2021). "Of high clinical relevance are people with type 2 diabetes who partake in shift work, who require specific guidance in terms of meal preparation and insulin regimens in order to achieve optimal glycaemic control." (PMID 34401953, 2021). "Biosynthetic or animal-source insulin is the most effective way for the management of type I diabetic patients as well as in patients with advanced type II diabetes who fail to well respond to oral hypoglycemic agents." (PMID 34803500, 2021). "For KEGG, pathways such as Maturity onset diabetes of the young, Type II diabetes mellitus, Insulin secretion, Morphine addiction, GABAergic synapse, and Circadian entrainment were enriched." (PMID 34307375, 2021). "Both type 1 and type 2 diabetes are related to insulin, a hormone produced in pancreatic β cells that signals the removal of glucose from the blood and stimulates the storage of glucose in the form of glycogen." (PMID 33458612, 2021). "Retinoids and retinoid-related proteins involved with signaling molecules linking obesity with the production of type II diabetes and in pancreatic β-cell biology/insulin secretion." (PMID 34725640, 2021).